THBS1 (thrombospondin 1)
Diseases named in the same sentence as THBS1 in open-access papers (continued):
Sharing a sentence is not in itself a finding about the gene and the disease.
Obesity (continued). "In conclusion, our findings suggest that the let-7a-5p/Srebf2 and let-7a-5p/Thbs1/PI3K-AKT-mTOR axes are crucial for lipid accumulation and that they may represent a potential mechanism for controlling lipid accumulation in obesity." (PMID 38255968, 2024). "Surprisingly, we did not detect any major effect of injury and obesity on the expression levels of TNF or the associated genes Bcl3, Errfi1, Irak3, Myd88, and Thbs1 in our obese model." (PMID 29922174, 2018). "Selected candidate genes Npr3 and Thbs1, as well as Gys2, a non-QTL gene that otherwise passed our enrichment criteria were characterised, revealing novel functional effects consistent with a contribution to obesity." (PMID 21915269, 2011).
diabetes (30 papers, 2009 to 2025). "Thrombospondin-1 (TSP-1) has been implicated in development of vascular diabetic complications and is expressed in developing arterial plaques." (PMID 19946412, 2009). "Another screening study of serum samples from patients with PDAC, chronic pancreatitis (CP), benign biliary disease, type 2 diabetes mellitus and healthy subjects by iTRAQ labeling showed that low levels of thrombospondin-1 (THBS1) up to 24 months prior to diagnosis were associated with PDAC." (PMID 31349663, 2019). "We showed that: diabetes is associated with lower EPC numbers; and the levels of anti-angiogenic factors such as thrombospondin-1 and − 2 and pro-angiogenic factors such as G-CSF and SDF-1 are correlated with EPC subtypes." (PMID 39186241, 2024). "Thbs1 has been identified as one of the markers in the early stages of diabetes and a key mediator in its development." (PMID 38764083, 2024). "The peptide antagonist, LSKL, can inhibit Thbs1 activity, thereby reducing diabetes-related complications resulting from Thbs1 upregulation." (PMID 38764083, 2024). "The results suggest that LOX, HIF1α, THBS1, TGFβ2, and ITGβ1 may be involved in the diabetes‐induced downregulation of FGF9, thus promoting the development of renal EMT." (PMID 40977522, 2025). "Earlier work from our laboratory demonstrates that high glucose, mimicking diabetes, and high leptin, mimicking obesity, upregulate the expression of a potent proatherogenic protein, thrombospondin-1 (TSP-1), in human and mouse aortic smooth muscle cells (SMC)." (PMID 36505365, 2022). "Identification using iTRAQ and validation using MRM of thrombospondin-1 (TSP-1) as a protein biomarker in patients at risk of developing pancreatic cancer, such as those with neo-onset diabetes, show that this condition impacts positively the diagnostic performance of CA19-9." (PMID 29865155, 2018). "Of the five, thrombospondin-1 (TSP-1) is the most well described in relation to inflammation and fibrogenesis in many diseases such as liver fibrosis, diabetes, multiple tumors and cardiovascular disorders." (PMID 34670505, 2021). "Increasing evidence suggests thrombospondin-1 (TSP-1), a potent proatherogenic matricellular protein, as a putative link between hyperglycemia and atherosclerotic complications in diabetes." (PMID 28345659, 2017). "While the molecular mechanisms of THBS4 in diabetes and COPD still require further clarification, intervening in THBS1 may be an effective therapeutic strategy." (PMID 39845878, 2024). "Further subgroup analyses by age, gender, smoking, drinking, hypertension, diabetes, and dyslipidemia did not observed significant differences in THBS1 mRNA expression was detected between IS cases and controls." (PMID 36212039, 2022). "A combination of α-1-antichymotrypsin (AACT), thrombospondin-1 (THBS1), and haptoglobin (HPT) outperformed CA 19−9 in distinguishing pancreatic cancer from normal controls (AUC = 0.95), patients with diabetes (AUC = 0.89), pancreatic cysts (AUC = 0.82), and chronic pancreatitis (AUC = 0.90)." (PMID 33800786, 2021). "The extracellular protein thrombospondin-1 (TSP-1), a kind of extracellular glycoprotein, is upregulated by the increased activity of some transcription factors and results in fibrosis by activating multiple pathways in diabetes." (PMID 32626782, 2020). "It has also been reported that THBS-1 affects CAD and diabetes." (PMID 32466277, 2020). "Diabetes did not alter genes encoding the two angiogenesis repressors sprouty (SPRY) and thrombospondin (THBS1)." (PMID 31001672, 2019). "Short disease duration without diabetes complications perhaps also helps to explain why the baseline elevations of PPBP, THBS1, and CDH1 were modest in this T2D population, though may additionally indicate that they are more sensitive markers of AIS due to LVO." (PMID 34926573, 2021).
lung carcinoma (29 papers, 2006 to 2025). "Changes in DNA-methylation and expression of THBS1 have been associated with atherosclerosis and cancer among smokers, while other reports have linked overexpression of THBS1 with higher lung cancer survival." (PMID 37208747, 2023). "In early stage of lung cancer, increased expression of thrombospondin-1 (TSP-1) in lung megakaryocytes and platelets inhibits endogenous angiogenesis and exerts antitumor effects." (PMID 38902986, 2024). "Studies have shown that THBS1 has a tumor-suppressive role in lung adenocarcinoma, and THBS1 is usually insufficiently expressed in lung cancer tissues." (PMID 33988228, 2021). "Pigment epithelium-derived factor (PEDF)-treated exosomes from lung cancer cells inhibit cytoskeletal remodeling by secreting THBS1, which reduces the vitality of lung cancer cells and inhibits cell invasion and migration." (PMID 34511114, 2021). "The context dependency of thrombospondin-1’s involvement in lung cancer initiation, primary tumor progression and the establishment of secondary tumors remain to be clarified." (PMID 33014869, 2020). "THBS1 has been shown to act as a tumor suppressor in lung cancer, and reduced expression of THBS1 indicate poor prognosis in NSCLC patients." (PMID 27634890, 2016). "THBS1 was in general underexpressed in lung cancer; in contrast, mRNA levels of THBS2 were markedly overexpressed in a number of datasets of non-small cell lung carcinoma (NSCLC), including lung adenocarcinoma (AC) and squamous cell carcinoma." (PMID 27513329, 2016). "THBS1 has been considered an inhibitor of angiogenesis and tumor progression in bladder and lung cancer." (PMID 17022822, 2006). "Furthermore, they suggest that the pro-metastatic properties of Staufen1 in lung cancer are at least partially mediated by THBS1." (PMID 35008641, 2021). "Altogether, our results suggest that regulation of THBS1 expression by Stau1 may be a key process involved in lung cancer progression." (PMID 35008641, 2021). "In AC lung cancer patients with a history of smoking, the survival rates (HR = 0.62) of those with higher mRNA expression of THBS1 were better than those with lower mRNA expression of THBS1." (PMID 27513329, 2016). "Interestingly, THBS1 inhibits exosom-induced lung cancer cell migration and invasion." (PMID 39165641, 2024). "Stimulation of THBS1 expression by TGF-β1 was observed in oral squamous cell carcinoma, lung carcinoma cells A549, skin keratinocytes HaCaT, and rat proximal tubular epithelial cells NRK52E." (PMID 33912465, 2021). "High expression of THBS1 or THBS4 is more sensitive to AZD6244, the inhibitor of MEK1 used to treat NSLC (nonsmall-cell lung cancer)." (PMID 34804159, 2021). "We next focused on investigating the changes in THBS1 and THBS2 mRNA expression in lung cancer subtypes." (PMID 27513329, 2016). "Genes encoding secreted factors, including osteopontin (OPN), chemokine (C-C motif) ligand 7 (CCL7) and thrombospondin 1 (TSP1) were identified, which enhanced tumorigenic properties of lung cancer cells indicative of their potential as targets for therapy." (PMID 26046767, 2015). "However, the expression pattern of THBS1 and THBS2 is different, and the specific role of THBS2 in different subtypes of lung cancer remains largely unclear." (PMID 27513329, 2016). "Most studies have focused on the role of THBS1 in lung cancer rather than other THBSs." (PMID 27513329, 2016).
prostate carcinoma (25 papers, 2016 to 2026). A carcinoma that arises from epithelial cells of the prostate gland. "THBS1 was found to be a direct target of epigenetic suppression by the enhancer of zeste homolog 2 (EZH2), which can directly regulate THBS1, thereby promoting neuroendocrine progression and angiogenesis in invasive prostate cancer." (PMID 39273281, 2024). "The result of network pharmacology delineated the roles of formononetin’s targets such CD74 and THBS1 in immune cells’ function of prostate cancer." (PMID 38874510, 2024). "Vice versa, the knockdown of THBS1 increased the growth and colony forming ability of prostate cancer cell." (PMID 38874510, 2024). "We further confirmed that TGFβ1-induced THBS1 is important for cancer cell invasion, as the knockdown of THBS1 in vitro, or knockdown of TβRI both in vitro and in vivo, inhibited the invasion of prostate cancer cells." (PMID 39304722, 2024). "In prostate cancer, THBS1 has been reported to trigger cell migration and the development of advanced prostate tumors." (PMID 39304722, 2024). "To further analyze the function of THBS1 in the migration and invasion of prostate cancer cells, we knocked down THBS1 in PC3U cells using siRNA." (PMID 39304722, 2024). "Enhancer of zeste homolog 2 (EZH2) directly targets THBS1, thus promoting neuroendocrine progression and angiogenesis in aggressive prostate cancer." (PMID 38203613, 2023). "HDAC2 induced by beta-adrenergic signaling promoted tumor angiogenesis and prostate cancer progression by suppressing thrombospondin-1 expression." (PMID 32292495, 2020). "A single study reported that thrombospondin 1 (TSP-1)-expressing MDSC-like cells are able to abrogate the metastatic spread of prostate cancer cells opening new insight on MDSC and metastasis relation." (PMID 32133298, 2020). "Histone deacetylase-2 (HDAC2) epigenetically represses the expression of THBS1, consequently inducing angiogenesis in prostate cancer." (PMID 31847842, 2019). "Thrombospondin-1, also a proteoglycan enriched in myocyte EVs, is an extracellular calcium-binding glycoprotein, of which upregulation has been shown to dose-dependently inhibit prostate cancer proliferation, migration and invasion." (PMID 41300368, 2025). "We also investigated THBS1 in human prostate cancer tissue using immunohistochemical staining." (PMID 39304722, 2024). "The interaction of ECM proteins with the TβRI in the migratory prostate cancer cells in response to TGFβ1 was demonstrated by several different techniques to reveal that THBS1 mediates cell migration by interacting with integrin subunit alpha V (ITGAV) and TβRI." (PMID 39304722, 2024). "Finally, we found that the high expression of THBS1 significantly correlates with the Gleason score (GS), tumor stage, and bone metastasis in prostate cancer." (PMID 39304722, 2024). "Additionally, Histone deacetylase-2 (HDAC2) inhibited the expression of THBS1, leading to the stimulation of angiogenesis and the acceleration of prostate cancer development via beta-adrenergic signaling." (PMID 39273281, 2024). "In addition, immunofluorescent staining indicated a higher level of THBS1 in bone metastatic prostate cancer." (PMID 39304722, 2024). "In the invasion assay, the knockdown of THBS1 prevented the invasion of prostate cancer cells." (PMID 39304722, 2024). "Although a previous study showed that THBS1 is associated with the development of advanced prostate cancer, the molecular function of THBS1 in the context of prostate cancer progression has previously not been uncovered." (PMID 39304722, 2024). "In prostate cancer, THBS1 inhibited neovascularization and tumor growth." (PMID 38874510, 2024). "Moreover, histone deacetylase-2 (HDAC2) suppressed THBS1 expression, subsequently induced angiogenesis, and promoted prostate cancer progression mediated by beta-adrenergic signaling." (PMID 38203613, 2023).
prostate carcinoma (continued). "Thus, ADRB2/PKA/CREB signaling increased neovascularization in xenograft models of prostate cancer by sustained epigenetic inhibition of the angiogenesis suppressor thrombospondin-1 TSP1." (PMID 30871232, 2019). "Expression array showed that in prostate cancer cells VPA induces the up-regulation of TSP1 (Thrombospondin-1), multiple TIMP (Tissue inhibitor of metalloproteinase) isoforms and TGFβ (Transforming growth factor β), while expression of IGF1 (Insulin like growth factor 1) and VEGF is decreased." (PMID 28671573, 2017). "One of the major functions of THBS1 in the prostate is to convert latent TGFβ into its active form, but it can also serve as a potential biomarker to distinguish benign prostatic hyperplasia from malignant prostate cancer in epithelia, suggesting its role in prostate cancer progression." (PMID 26588813, 2016). "THBS1 belongs to a group of tumorigenic ECM proteins induced via TGFβ signaling in CRPC cells, and high expression of THBS1 in human prostate cancer tissues correlated with the degree of malignancy." (PMID 39304722, 2024). "In the immune cell cluster of prostate cancer, formononetin targeted CD74, TNF, HBB, THBS1, INSR, CXCR4, and HSP90AA1." (PMID 38874510, 2024). "A set of transcripts including Caveolin‐1 (CAV1), TMP2, THBS1, and CTGF were found to be successful in discriminating clinically insignificant (Gleason = 6) disease from clinically significant (Gleason > 8) prostate cancer." (PMID 34596356, 2021). "Recently two novel cancer-related glycoproteins, thrombospondin 1 (THBS1) and cathepsin D (CTSD) were proposed as blood-based biomarkers that outperformed PSA in distinguishing benign disease from prostate cancer in men with enlarged prostate gland." (PMID 33924671, 2021). "Interestingly, in TCGA database, the expression of TβRI and THBS1, as well as TβRI and ITGAV in prostate cancer shows the correlations." (PMID 39304722, 2024). "Yet to our knowledge, and following exploration of the TCGA PanCancer Atlas dataset available via cBioportal, an altered expression of AKT1, CAV1, THBS1, or TIMP2 has not been previously associated with progression to aggressive prostate cancer." (PMID 34596356, 2021). "To further investigate the role of THBS1 in tumor invasion and metastasis, we applied an orthotopic human metastatic CRPC xenograft model that was previously established in our laboratory to elucidate the molecular mechanisms regulating lymphatic metastasis of prostate cancer." (PMID 39304722, 2024). "For example, thrombospondins (THBS) are ECM glycoproteins involved in the inhibition of angiogenesis that were shown to regulate the normal prostate in vivo, but also to potentiate the cell migration and development of advanced prostate tumors (THBS1) and prostate cancer bone metastasis (THBS2)." (PMID 38255186, 2023). "Namely, initial papers on the potential of THBS1 and CTSD signature in prostate cancer were published in 2017, 2019, and 2020 and were based on the earlier analyses of the serum proteome in metastatic castration-resistant prostate cancer patients and the PTEN conditional knockout mouse model." (PMID 38255186, 2023).
ovarian carcinoma (23 papers, 2009 to 2024). A malignant neoplasm originating from the surface ovarian epithelium. "COL1A1, COL11A and Thrombospondin-1 (THBS1) are indeed associated with tumour invasiveness and poor prognosis in ovarian cancer." (PMID 34238352, 2021). "We previously demonstrated that THBS1 protein expression was associated with clinical outcome in women with advanced epithelial ovarian cancer (EOC) who were treated with taxane and platinum-based chemotherapy regimens." (PMID 24195060, 2013). "THBS1 is known to play a role in cell-cell and cell-matrix interactions that are key for metastases progression to the peritoneal space in ovarian cancer." (PMID 34868914, 2021). "THBS1 mRNA expression levels also significantly correlate with poor prognosis for ovarian carcinoma patients, while both THBS1 and CD47 expression are associated with being decreased overall, as well as progression free survival." (PMID 34638503, 2021). "Further, ovarian cancer patients with high THBS1 expression and treated with platinum-based chemotherapy have longer survival and is an independent prognostic factor in multivariate analysis." (PMID 34090482, 2021). "In another study involving patient-derived ovarian carcinoma xenografts, the lower expression of THBS1 in tumor cells was identified as an important factor." (PMID 34064977, 2021). "Although trends indicate an increase in ACTB and THBS1 expression in ovarian cancer patients compared to healthy control subjects, differences in ΔCq values were not significantly different due to low sample numbers." (PMID 34868914, 2021). "We are continuing to evaluate THBS1 expression and promoter methylation in ovarian cancer specimens that contain cancer cells as well as the surrounding stroma." (PMID 24195060, 2013). "Further analysis is needed to understand the THBS1 post-transcriptional modifications in ovarian cancer." (PMID 24195060, 2013). "Consistently, differential gene expression among TCGA showed a trend for both TSP-1 and CD47-encoding genes (i.e., THBS1 and CD47, respectively) to be upregulated in ovarian carcinoma patients, especially with elevated THBS1 mRNA expression in case of vascular and lymphovascular invasion." (PMID 34638503, 2021). "Interestingly, the gene product of related THBS1 is expressed in ovarian cancer cell lines and ascites fluid of patients." (PMID 24175302, 2013). "We evaluated THBS1 gene, mRNA, and protein expression in a subset of six ovarian cancer cell lines." (PMID 24195060, 2013). "Two identified biomarkers among differentially expressed proteins, SPARC and THBS1, had lower plasma concentrations in healthy BRCA1/2 variant carriers than in ovarian cancer patients with the BRCA1/2 variant; concentration of two proteins increased at the onset of ovarian cancer." (PMID 34064977, 2021). "Mone 1062—one of the mones in the identified cluster—was additionally highly correlated with ECM2, THBS1 and THBS2, which have been suggested to play a significant role in ovarian cancer drug resistance and metastasis." (PMID 35676395, 2022). "In ovarian cancer, IGFBP3 inhibits angiogenesis by regulating intracellular THBS1 expression." (PMID 39040110, 2024).